EGFR (epidermal growth factor receptor)
Diseases named in the same sentence as EGFR in open-access papers (continued):
Sharing a sentence is not in itself a finding about the gene and the disease.
cancer (continued). "The expression of the epidermal growth factor receptor (EGFR) is highly regulated in normal cells, whereas some cancer cells have high constitutive levels." (PMID 26493292, 2015). "Overexpressed EGFR transmits multiple signals to cell for accelerated growth and cellular longevity, and plays a key role in the carcinogenesis of different types of cancer." (PMID 25789858, 2015). "EGFR mutations and overexpression have further been shown to modulate sensitivity to these EGFR-targeted therapies in NSCLC and several other types of cancers." (PMID 25962919, 2015). "Increasing evidence suggests that EGFR pathways are involved in the progression of cancer of the bone, soft tissue, breast, and lungs." (PMID 26503469, 2015). "Scientific efforts aiming at dissecting the cancer biology of TNBC have revealed several promising therapeutic targets including epidermal growth factor receptor (EGFR), a critical membrane-bound receptor tyrosine kinase for cancer progression." (PMID 26513016, 2015). "Adding to complexity, TGF-α, HB-EGF, and AR were shown to be released following EGFR transactivation by GPCRs in a variety of cancer cell lines." (PMID 26729094, 2015). "New treatment strategies such as epidermal growth factor receptor (EGFR) inhibition by cetuximab have been shown to prolong survival, but 5-year survival rates of patients with locally advanced cancers are still at 50% or below." (PMID 25890004, 2015). "Cancer cell lines were utilized for further experiments to elucidate the roles of EGFR and HER-2 in EC cells." (PMID 26673416, 2015). "In this elegant study they were able to distinguish between stromal (mouse) and cancer (human) cell specific changes of total and of phosphorylated EGFR levels." (PMID 25884419, 2015). "Xenograft study revealed in vivo anticancer efficacy of isoliquiritigenin against cancer cells expressing mutant EGFR." (PMID 26798565, 2015). "The results revealed a wide variety of miRNA involved in several signaling pathways, such as cancer, apoptosis, and EGFR signaling pathway." (PMID 26563758, 2015). "Over-expression of the human epidermal growth factor receptor (EGFR/HER1) pathway is a feature of many cancers and a potential therapeutic target." (PMID 25674538, 2015). "The activation of the tyrosine kinase domain of EGFR activates EGFR pathways and results in the initiation of cancer proliferation, increased metastasis potential and neoangiogenesis." (PMID 25714021, 2015). "Previous studies showed that NR4A1 in combination with p300 activated Sp-regulated genes such as survivin, bcl-2 and EGFR in cancer cells." (PMID 26035713, 2015). "Six cancer-associated molecules (HB-EGF, EGF, EGFR, sCD26, VEGF, and Calprotectin) were investigated in this study." (PMID 25992884, 2015). "The PentaPanel platform assesses single nucleotide polymorphisms in 56 hotspots of the 5 most clinically relevant cancer genes, KRAS, NRAS, BRAF, EGFR and PIK3CA for a total of 221 detectable mutations." (PMID 26435479, 2015). "Epidermal growth factor receptor tyrosine kinase (EGFR-TK) inhibitors are useful in treating different advanced human cancers; however, their clinical efficacy varies." (PMID 25950441, 2015). "In this study, mRNA of EGFR and c-Met was also decreased by WJ, indicating that both decrease in EGFR protein stability and inhibition of EGFR transcription contribute to the anti-cancer effect of HDACi." (PMID 25980579, 2015). "Human epidermal growth factor receptor (EGFR) which belongs to EGFR family is overexpressed in a significant proportion of cases of GC to promote metastasis of cancer." (PMID 25948494, 2015). "When overexpressed and activated, EGFR initiates a complex intracellular signal transduction cascade promoting cancer cell proliferation, apoptosis, angiogenesis and metastasisis." (PMID 25959250, 2015).
cancer (continued). "Several studies have reported extensive cross-talk between IR (insulin receptor)/IGF1R (insulin-like growth factor-1 receptor) and EGFR/ErbB signaling pathways contributing to acquired drug resistance in various cancers." (PMID 25599599, 2015). "Epidermal growth factor (EGF), an upstream effector of PTTG, induces PTTG expression by a paracrine mechanism, leading to activation of the EGF receptor (EGFR) and promoted cancer cell proliferation." (PMID 26516926, 2015). "WJ induced c-Cbl up-regulation to degrade EGFR through lysosome pathway, and knockdown of c-Cbl reversed WJ-induced anti-cancer effect." (PMID 25980579, 2015). "The definitions of EGFR amplification varied in different cancer types and even within diffuse gliomas, the cut-off criteria varied in different studies." (PMID 26369702, 2015). "Despite the complex nature of EGFR signaling, targeted therapeutic approaches have become an intense focus in drug development for various cancers." (PMID 26382850, 2015). "Numerous studies have implicated RPTKs as oncogenes, and several RPTKs such as EGFR, VEGFR, HER2 have been selected as targets in cancer therapy." (PMID 25884558, 2015). "The proven clinical utility of EGFR inhibition in the treatment of cancer makes EGFR targeted drugs an attractive approach to ACP treatment." (PMID 25990246, 2015). "These important cell signaling interactions between AMPK and HER2/EGFR have implications with respect to prevention and treatment of cancer." (PMID 26143491, 2015). "Aberrant activation of EGFR has been shown to play a critical role in cancer cell survival and development." (PMID 25776829, 2015). "A recent experimental study revealed that vorinostat treatment increased the acetylation of EGFR, which leads to enhanced EGFR phosphorylation in cancer cells." (PMID 25552401, 2015). "EGFR is often constitutively stimulated in cancer cells owing to the binding of ligands such as EGF." (PMID 25723471, 2015). "We show that the p38 MAP kinase-dependent, EGFR tyrosine kinase (TK)-independent EGFR internalization induced by ultraviolet light C (UVC) or the cancer therapeutic cisplatin, is followed by diversion from the canonical endocytic pathway." (PMID 26066081, 2015). "As a consequence, the treatment of Caski and CSCC1 cancer cells with the anti-EGFR antibody cetuximab resulted in a higher production of IFN-γ and TNF-α-induced cytokines than when the cancer cells were treated with the control anti-CD20 antibody rituximab." (PMID 26055519, 2015). "EGCG also decreases cell surface EGFR by inducing the internalization of EGFR into endosomal vesicles, leading to inhibiting the activation of the receptor and exerting anti-cancer effects." (PMID 25789501, 2015). "Overall, this study will be helpful in the area of computational designing of novel anti-EGFR molecules used for cancer treatment." (PMID 25880749, 2015). "The dual expression of NeuGcGM3 and EGFR in a variety of human malignant tumors, including NSCLC, was evidenced." (PMID 26634172, 2015). "Given its massive presence in several tumors and its key role in metastasis, EGFR is defined as a principal target in anti-cancer therapies." (PMID 25629807, 2015). "All of them were reported to contribute to the inhibition by AECS on high-EGFR expression cell growth, indicating the efficacy of AECS as a potential strategy against high-EGFR-expressing cancers." (PMID 26593947, 2015).
cancer (continued). "The S100A8 and epidermal growth factor receptor (EGFR) proteins are proto-oncogenes that are strongly expressed in a number of cancer types." (PMID 25789858, 2015). "The reason for choosing midostaurin, enzastaurin, and gefitinib as inhibitor for S100A8 and EGFR is the recent research showing that EGFR-targeted therapies using kinase inhibitors are effective in many cancer patients." (PMID 25789858, 2015). "Gefitinib (Iressa) is an orally administrable anticancer agent against EGFR kinase and shows efficacies against various cancers with EGFR activation including breast, lung, colon and other cancers." (PMID 25955731, 2015). "mTOR and EGFR inhibitors have already been identified as a synergistic combination in various cancer cell types, despite clinically observed toxicity." (PMID 25824484, 2015). "EGFR signaling is one of the major upstream regulators of mTOR, and its activation induces resistance to crizotinib as well as cancer stemness." (PMID 26517679, 2015). "PC9 (EGFR exon 19 deletion mutant; Gefitinib-vulnerable cells) and A549 (EGFR wild type; Gefitinib-resistant cells) cancer cells were used to evaluate the in vitro therapeutic benefits of combining Gefitinib and Tamoxifen." (PMID 25692143, 2015). "In vitro studies of MET and EGFR have shown that a single amplified receptor tyrosine-kinase can determine growth and survival of different cancer cell lines (lung, gastric)." (PMID 26319934, 2015). "Despite some clinical success, EGFR and HER2 inhibitors invariably lose efficacy as cancers develop resistance, often arising from enhanced ligand-dependent ErbB signaling." (PMID 26477568, 2015). "Epidermal growth factor receptor (EGFR) is often constitutively stimulated in many cancers owing to the binding of ligands such as epidermal growth factor (EGF)." (PMID 25723471, 2015). "Several previous studies showed that EGFR signaling is one of the potentially targeted pathways for identifying anticancer drugs and treatment strategies for various cancers." (PMID 26763900, 2015). "One patient had scarce EGFR expression in both normal and cancer tissues, while the other patient showed intense overexpression in both tissues." (PMID 26655729, 2015). "Hopefully, the selection of EGFR-positive cancers will enrich for patients who will benefit from anti EGFR therapy." (PMID 25649416, 2015). "Our data reveal that EGFR mutant cancers that transform to SCLC also undergo significant epigenetic changes." (PMID 25758528, 2015). "Both EGFR and Ki67 have been used extensively in IHC analyses as markers to characterize proliferation in cancers of the oral cavity and esophagus in both humans and mice." (PMID 25714027, 2015). "The EGFR-driven signaling network, as a key player of cell proliferation and differentiation, is one of the many systems exploited by cancer cells to enable their survival in the presence of environmental perturbations." (PMID 25885672, 2015). "The EGFR TK domain has been identified as suitable target in cancer therapy and tyrosine kinase inhibitors such as erlotinib have been used for treatment of cancer." (PMID 26041145, 2015). "Epidermal growth factor receptor signaling has an important role in many cancers, as cellular proliferation is mainly controlled by growth factors and their receptors." (PMID 25688333, 2015). "We showed that mTOR and phosphodiesterase 4D (PDE4D) strongly correlate in resistant EGFR-mutant cancer cell lines." (PMID 26639561, 2015). "It has been demonstrated that crosstalk between GPCRs and EGFR contributes to cancer malignant progression." (PMID 26526356, 2015). "A key challenge for TKIs (including those targeting EGFR) in cancer is the development of acquired resistance, with many patients showing disease progression not long after the initial response." (PMID 25742484, 2015).
cancer (continued). "EGFR, HER2, KRAS, PTEN and PI3K were sequenced for cancer-associated mutations; in addition, HER2 and EGFR copy numbers or EML4-ALK (echinoderm microtubule-associated protein-like 4–anaplastic lymphoma kinase) rearrangement were evaluated by FISH." (PMID 26247735, 2015). "The four GDDCs contain a 10–30 mer length loop targeting epidermal growth factor receptor (EGFR) mRNA, which is transcribed at high levels in cancer cells." (PMID 25905703, 2015). "Recently, EGFR has been reported to use SOS1 to drive constitutive activation of Nuclear Factor κB (NFκB) in cancer cells." (PMID 25980493, 2015). "The EGFR pathway is an appropriate target for cancer therapy, and several agents that block this pathway have been developed." (PMID 25532027, 2015). "For example, overexpression of Transforming growth factor-alpha (TGF-α), one of the main ligands of the EGFR, has been observed in various of malignant tumors such as kidney cancer, pancreatic cancer, colon cancer and breast cancer." (PMID 26503469, 2015). "Our findings indicate a new mechanism of erlotinib and a new strategy to enhance EGFR-targeted cancer therapy through cotargeting miRNAs." (PMID 26593208, 2015). "This process is frequently deregulated in cancer cells, leading to enhanced EGFR levels and signaling." (PMID 26528697, 2015). "Several EGFR-derived CTL epitopes have been identified; however, the frequency of high-avidity EGFR-specific CTLs seems to be low in patients with EGFR-expressing cancers, because EGFR is a self-antigen that induces tolerance." (PMID 25532027, 2015). "Results of this study will also prove to be useful in designing potent anti-tumorals based on EGFR TK inhibition to further develop drugs against cancer." (PMID 26041145, 2015). "In other terms, the optimization of the system for physiological EGFR levels also harbours an intrinsic weakness, which is exploited by cancer cells to obtain a proliferative advantage." (PMID 26264748, 2015). "Epidermal growth factor receptor (EGFR) has been shown to be overexpressed in many human cancers, including lung, central nervous system, head and neck, bladder, pancreas, and breast; and it correlates with poor prognosis." (PMID 26673416, 2015). "The combination of Gef plus TAM even gets treatment response in EGFR wild type cancer cell line study." (PMID 25692143, 2015). "One report has suggested that EGFR physically associates with and stabilizes SGLT1 to promote glucose uptake into cancer cells." (PMID 26023239, 2015). "Identification of cancer-associated mutations has become standard care for cancer treatment; examples of such include RAS mutations in metastatic colorectal carcinomas or EGFR mutations in lung cancer." (PMID 26366557, 2015). "Defects in the implementation of feedback loops in the EGFR-driven signaling network can lead to the emergence or progression of cancers." (PMID 25885672, 2015). "A recent study also demonstrated that NKX2.1 is required to sustain EGFR survival signaling in human cancer." (PMID 25154973, 2015). "As well, combination of MAbs with TKIs, e.g., trastuzumab plus anti-EGFR/anti-ErbB2 such as lapatinib or pertuzumab, revealed of clinical benefit for recurrent cancers following trastuzumab treatment for instance." (PMID 25699077, 2015). "One group of agents that target the kinase domain of EGFR, called tyrosine kinase inhibitors (TKIs), are clinically active and broadly applied in the treatments of cancers such as non-small-cell lung carcinoma (NSCLC)." (PMID 25993617, 2015). "In cancer cells, EGFR and its downstream pathways can be constitutively activated independent of external signals." (PMID 26378037, 2015). "miRNA-200 regulates EMT in BC, and its expression increases the sensitivity of cancer cells to epidermal growth factor receptor (EGFR) inhibitors." (PMID 26729098, 2015). "S100A8 and EGFR do play an important role in malignancy and thus considered as potential drug targets for cancer therapeutics development." (PMID 25789858, 2015).
cancer (continued). "The epidermal growth factor receptor (EGFR) signaling network is crucial in the regulation of cancer cell proliferation, migration and survival." (PMID 25885672, 2015). "To confirm the results of EGFR copy number analysis we reanalyzed a panel of cancer samples, including all samples with EGFR amplification, with the use of qPCR and ddPCR." (PMID 25719557, 2015). "Epidermal growth factor receptor (EGFR) is a molecular target of oncotherapy in certain kinds of cancer including non-small cell lung cancer (NSCLC)." (PMID 26418897, 2015). "For example, quercetin, a natural flavonol, is an inhibitor of different kinases involved in cancer progression, such as epidermal growth factor receptor (EGFR), cyclin-dependent kinases and Aurora-A." (PMID 26036640, 2015). "EGFR signaling network has an interactive nature, being one of the most deregulated molecular pathways found in human cancer." (PMID 25784483, 2015). "The treatment of patients with EGFR based inhibitors as targeted therapy thus has shown a significant reduction in the cancer progression." (PMID 25880749, 2015). "Meanwhile, it is anticipated that EGFR inhibitors of second- or third-generation will be coming out to overcome target-resistant cancers." (PMID 26370727, 2015). "The remarkable variation among cancer patients in response to EGFR-targeted therapy remains a daunting challenge." (PMID 25871473, 2015). "Previous phase III studies were conducted to compare PFS between EGFR-TKI and an anti-cancer agent as first-line therapy for EGFR mutated NSCLC patients." (PMID 26262682, 2015). "The EGFR vIII, which lacks the ability of ligand binding, is overexpressed and constitutively active in cancer cells of glioblastoma multiforme." (PMID 26378037, 2015). "Increased activation of other members of the ERBB family of tyrosine kinases has also been described, as compensatory activation of ERBB2 and ERBB3 was noted after EGFR withdrawal in GBM cancer-stem-cell lines." (PMID 25688333, 2015). "The epidermal growth factor receptor (EGFR) ligand amphiregulin (AR) plays a central role in branching morphogenesis in organs and is expressed both in healthy and in cancer tissues." (PMID 25744849, 2015). "EGFR is frequently overexpressed in many human cancers and correlates with cancer progression, metastasis, and poor prognosis." (PMID 26378037, 2015). "Activation of protein tyrosine kinase (PTK) is a common feature of cancer and many drugs targeting PTKs, such as epidermal growth factor receptor (EGFR)-tyrosine kinase inhibitors, have been introduced." (PMID 26134684, 2015). "Epidermal growth factor receptor (EGFR) is a receptor protein tyrosine kinase that plays fundamental roles in normal and cancer cells." (PMID 26025929, 2015). "Amplification, overexpression, or mutations of epidermal growth factor receptor (EGFR) leading to the activations of both Ras-ERK and Ras-PI3K-Akt signaling pathways are detected in various human cancers." (PMID 26384305, 2015). "The epidermal growth factor receptor (EGFR) is one of the key contributors that contribute to cancer hallmarks in GBM." (PMID 26134617, 2015). "In this context, miRNAs regulate the EGFR signaling; vice versa, EGFR signaling has an impact on the miRNA profiling of cancer cells." (PMID 26064956, 2015). "Since the time EGFR was identified as a cancer target, a number of clinically approved monoclonal antibodies (mAbs) have been developed." (PMID 26491668, 2015). "Recently, it has also been shown that NTR1 gene is a target of the Wnt/APC oncogenic pathways connected with the β-catenin/Tcf transcriptional complex and NT can stimulate cancer proliferation in an EGFR-dependent mechanism." (PMID 26215716, 2015).